YAP1 (Yes1 associated transcriptional regulator)
Diseases named in the same sentence as YAP1 in open-access papers (continued):
Sharing a sentence is not in itself a finding about the gene and the disease.
tumor (continued). "EHEs have been characterized by tumor-specific WW domain-containing transcription regulator 1(WWTR1)-calmodulin-binding transcription activator 1 (CAMTA1) translocations, and recently, a novel Yes-associated protein 1 (YAP1)-transcription factor E3 (TFE3) gene fusion was identified in EHEs." (PMID 26840265, 2016). "Indeed, down-regulation of YAP1 in BGC-823 GC cells obviously reduced tumor growth in vivo." (PMID 27835600, 2016). "In addition, YAP1 signalling target genes were also highly expressed in HCC tumours." (PMID 27905400, 2016). "Thus, YAP1 is essential for the self-renewal maintenance of liver CSCs and tumour initiation." (PMID 27905400, 2016). "However, little is known about the role of YAP1 in ALV-J induced tumours." (PMID 24694742, 2014). "However, the inverse correlation of cyclin D1 and YAP1 protein expression observed in the randomised tumour material remained after removing the CCND1 amplified cases from the analysis, indicating additional functions for maintaining the negative relationship between the two proteins." (PMID 24559095, 2014). "Here, our findings identified the ANLN/RhoA/YAP1/TEAD1 positive feedback axis in ICC, which was essential for cytokinesis and tumor growth." (PMID 41513610, 2026). "CCL24 did not directly alter CD8+ T cell populations; instead, CCL24+ tumor cells recruited CCR3+ TAMs, which promote immunosuppression by promoting nuclear translocation of YAP1, a key transcription factor of the Hippo pathway." (PMID 41694595, 2026). "In this study, we demonstrated that ANLN contributed to ICC growth via the RhoA/LATS1/YAP1 axis, establishing a link between ANLN and the Hippo pathway, which broadened the understanding of the role of ANLN in tumor." (PMID 41513610, 2026). "Histologically, EHE is a malignant tumor composed of vascular endothelial cells accompanied by a distinctive myxoid-hyaline transformation of the mesenchyme with WWTR1::CAMTA1 and YAP1::TFE3 fusion genes." (PMID 39917171, 2025). "For example, YAP1 enhances the expression of SOX12 by upregulating FOXP4 in gastric cancer, thereby regulating cancer cell stemness and promoting tumor initiation and progression." (PMID 40303290, 2025). "The treatment of AZD9291 alone did not affect BRD4, APT1, YAP1, and p-YAP1 and MST1 palmitoylation in tumor cells, whereas the treatment of NHWD870 alone reduced the expression of BRD4, APT1 and YAP1 but enhanced YAP1 phosphorylation and MST1 palmitoylation." (PMID 41184230, 2025). "The proportion of OS importance accounted for by risk factors of TNM staging, degree of tumor differentiation, YAP1 expression, COPB2 expression, tumor number, and tumor size in the ANN model was 0.23, 0.2168, 0.1823, 0.1338, 0.1288, and 0.1083, respectively." (PMID 40191726, 2025). "Pathway inactivation leads to YAP1/TAZ nuclear accumulation, where they interact with multiple oncogenic pathways (NOTCH, MAPK, Wnt) to drive stemness, EMT, drug resistance, and tumor progression." (PMID 41438763, 2025). "First, small-molecule agents can be developed to enhance LATS2 activity or inhibit YAP1, thereby promoting LATS2 phosphorylation and reinstating its tumor-suppressive function." (PMID 41256331, 2025). "Clinically, tumor tissue immunohistochemistry (IHC) staining is used to measure the protein expression of four transcription factors (ASCL1, NEUROD1, POU2F3, and YAP1) to identify SCLC subtypes." (PMID 40285610, 2025). "In this model, YAP1 upregulation suppressed CXCL16-driven CD4+/CD8+ TIL recruitment and increased MMP7 expression, resulting in elevated RCB scores and reduced tumor remission." (PMID 40731926, 2025). "YAP1 was expressed in both As_I and RT4 tumors and displayed mostly cytoplasmic staining and some nuclear expression in both tumor types." (PMID 40643470, 2025). "YAP1 and TAZ are the primary downstream effectors of the highly conserved Hippo tumor suppressor pathway." (PMID 40977060, 2025).
tumor (continued). "The combination of YAP1 inhibitor, verteporfin and DDP enhances anti-tumor immunity by regulating the interaction between YAP1 and cGAS-STING in the tumor microenvironment, providing new insights into a combined chemotherapy strategy for HCC." (PMID 40918140, 2025). "Galectin-3 plays a key role in tumor progression and metastasis through c-MYC upregulation and YAP1/RalA/RalBP, conferring an aggressive phenotype." (PMID 40149589, 2025). "Simultaneously, it induces tumor cell apoptosis and inhibits proliferation through pathways such as PI3K/YAP1/TAZ, PI3K/Akt, EGFR, and NF-κB, demonstrating high safety." (PMID 41156537, 2025). "At the origin stage, Tianyu Shen and colleagues reported that YAP1 promotes the transition from NFs to CAFs and helps sustain CAF pro-tumor programs." (PMID 41514658, 2025). "The canonical tumor suppressor function of STK3 was considered to be largely dependent on regulating the phosphorylation and then degradation of active YAP1." (PMID 40604818, 2025). "Conversely, GABAB receptors show tumor‐suppressive effects, inhibiting the proliferation of HCC and CRC by downregulating cAMP and blocking the Hippo/YAP1 pathway." (PMID 41415714, 2025). "There was a strong correlation between FAK and YAP1 at the protein level at stages I and III tumor groups in our local CRC patient cohort." (PMID 40959971, 2025). "YAP1 shRNA knockdown and pharmacological inhibition using TEAD inhibitor K-975 in MSTO-211H cells engrafted in a mouse model prevented tumor initiation and induced tumor regression." (PMID 41347094, 2025). "Senescent endothelial cells secrete exosomal SLC1A5, which is taken up by tumor cells and suppresses ferroptosis in tumor cells via the EGFR/SRC/YAP1/GPX4 pathway, thereby promoting gastric cancer progression." (PMID 40919170, 2025). "In conclusion, our study identifies PP1γ as a key regulator of YAP1 dephosphorylation and stem cell marker expression in ESCC, promoting tumor growth, invasion, and metastasis." (PMID 40626009, 2025). "Given its promoting function in the YAP1 phosphorylation and degradation process, STK3 is canonically considered as a tumor suppressor gene." (PMID 40604818, 2025). "In neuroendocrine cells, MYC activates Notch to dedifferentiate tumor cells, promoting a temporal shift in SCLC from ASCL1+ to NEUROD1+ to YAP1+ states." (PMID 40433367, 2025). "This is consistent with reports that ITGA11 expression in CAF is required for CAF-induced tumor cell invasion and that CAF deposit ECM tracks enriched with the YAP1 target gene and C3 marker ITGB5, which serve as guidance cues for cancer cell migration." (PMID 41327318, 2025). "Our functional analysis reveals a strong dependence of a fraction of CRC tumor cell lines on the integrin‐FAK pathway and its crosstalk with YAP1 and the BRD4‐MYC axis." (PMID 40959971, 2025). "Thus, our findings demonstrate the novel function of the CK2α-DUB3 axis in tumor progression by stabilizing YAP1 and highlight that targeting this axis might be an appealing strategy in human cancers with the aberrantly upregulated YAP1." (PMID 39827153, 2025). "In HCC, METTL3 promotes tumor growth by regulating oncogenic and tumor-suppressing genes, including SNAIL, YAP1, LINC00958, and SOCS2." (PMID 40302799, 2025). "In summary, comparing tumor growth in NSG and C57BL/6 mice, our results indicate that genetic and pharmacological attenuation of YAP1 significantly inhibits the tumor development in immune-competent and NSG mice." (PMID 39630608, 2024). "ASCL1 inversely correlates with YAP1 signaling, and in GEMMs of SCLC, expression of constitutively active Yap1 resulted in tumor phenotype switching by upregulation of Notch2 and downstream Rest and Hes1." (PMID 39456533, 2024). "YAP1 fosters the differentiation of Tregs, particularly by enhancing the expression of TGF-β receptor 2, thereby promoting immunosuppression in the tumor niche." (PMID 38550587, 2024).
tumor (continued). "In summary, we demonstrated that TRIM65 serves as a central oncogene through the activation of YAP1 and up‐regulation of UDP‐GlcNAc and FFA levels, thus promoting the tumor immunosuppressive microenvironment in HCC." (PMID 39005234, 2024). "Consistent with the high YAP1 mRNA expression seen in SCLC-Y cell lines, strong YAP1 protein expression was observed in all tumor cell lines within the SMARCA4-UT cluster and NSCLC cluster." (PMID 38180245, 2024). "YAP1 therefore serves as a mechanosensor that transduces mechanical stimuli to intracellular signals to promote survival, EMT and tumor progression in RCC cells." (PMID 39123485, 2024). "Western blots confirmed downregulation of SRC/YAP1 and SRC/RHOA signaling axis in the DAB2 downregulation cells, and validated tumor growth inhibition of DAB2." (PMID 38481347, 2024). "Activated YAP1 upregulates the secretion of IL-6 and TNF-α from tumor cells, as well as colony-stimulating factor 1-3 (CSF1-3), CXC motif chemokine ligand 5(CXCL5), PGE2, COX2, and other factors that recruit MDSCs." (PMID 38550587, 2024). "On the other hand, circ_0011058 is another circRNA that mediated in vivo tumour growth and angiogenesis and facilitated cell proliferation in PTC cell lines via controlling YAP1 expression and sponging miR-355-5p." (PMID 39558949, 2024). "In terms of the mechanism, we found that miR-21-5p carried by TAM-EVs activated HIF-1α in ECs through VHL and LATS1, forming a YAP1/HIF-1 positive loop, which plays a crucial role in promoting tumor angiogenesis." (PMID 38602536, 2024). "With YAP1 knockdown and NF2 reconstitution, they found that tumor growth and proliferation was inhibited." (PMID 39796693, 2024). "Research on YAP1 and TAZ has shown that these transcriptional cofactors have a multifaceted role in tumor growth." (PMID 39431199, 2024). "In turn, YAP1 regulates endothelial function by controlling the expression of ANG-2, which impacts tumor angiogenesis." (PMID 38550587, 2024). "During tumorigenesis driven by Apc/Kras, PCs share features with the YAP1-dependent RSC identity, and further activate TGFβ and WNT signaling in their conversion to bona fide tumor cells." (PMID 38902475, 2024). "CA3 was identified through a TEAD reporter transcription screen and was shown to effectively suppress YAP1/TEAD transcriptional activity and tumor growth in mouse models." (PMID 39624057, 2024). "YAP1 and TEAD1 transcript levels were effectively found to increase in GBM tissues, whereas those of TAZ remained unchanged among the healthy anti‐tumour tissue data analysed." (PMID 39718433, 2024). "YAP1 function is required for CAF to remodel ECM production and increase tumor stiffening, which is consistent with the potential role of YAP1 in stroma as a physical barrier reducing T cell content." (PMID 38346978, 2024). "For instance, fusions of oncogenic proteins TAZ, YAP1, and HIPK2 preserve their tumor-promoting function, while fusions of tumor suppressors, such as NF2, LATS1, FAT1, PTPN14, DCHS2, TAOK1, and TAOK3, results in loss of their function." (PMID 38499647, 2024). "The expression levels of CPNE3, YAP1, and CYR61 were remarkably reduced in the tumor tissues of the CPNE3-silenced group." (PMID 38493426, 2024). "The expression of CPNE3, YAP1, CYR61, and RAD51 proteins in tumor tissue samples from 100 randomly selected patients with GC was examined using continuous-section IHC labeling." (PMID 38493426, 2024). "Verteporfin, the inhibitor of YAP1, downregulated IL-6, CSF1-3, and CXCL5, which compel MDSCs in tumor." (PMID 38550587, 2024). "Tumor tissues from the PDX models were analyzed by WB and IHC, and the results indicated that YAP1 and CYR61 protein levels significantly decreased when CPNE3 was downregulated." (PMID 38493426, 2024). "In the present study, we confirmed that miR-34a and miR-605-5p act as tumor suppressors and upregulate YPEL3 expression by inhibiting YAP1 expression." (PMID 39345743, 2024).
tumor (continued). "A positive relationship between tumor YAP1 and TET1 levels was then validated in MST1/2−/− mouse tumor tissues and clinical HCC tissues." (PMID 38967794, 2024). "The inhibition of YAP1 induces the restriction of PCK1 on gluconeogenesis and restores the anti-tumor effect on HCC." (PMID 38550587, 2024). "We report for the first time that miR-34a and miR-605-5p function as tumor suppressors by upregulating YPEL3 and downregulating YAP1 expression." (PMID 39345743, 2024). "Further, we collected tumor tissues and found that HMGCS1 overexpression rescued CSN6 KD‐mediated decreased cholesterol and TG levels, and YAP1 target gene expression." (PMID 38308184, 2024). "YAP1 expression was also high in the tumor samples, but YPEL3 levels were relatively lower in the tumor samples than in the normal samples." (PMID 39345743, 2024). "Remarkably, co-targeting Yap1 by shYap1 and Cox2 by Cel-treatment converted Gem-resistant late-stage PDACs to highly Gem-sensitive with one PDAC tumor regressed to become undetectable." (PMID 39468013, 2024). "YAP1 and TBX5 form a complex with β-catenin, which localizes to the promoter of anti-apoptotic genes, enhancing their anti-apoptotic effects in tumor cells." (PMID 38965548, 2024). "YAP1 is a protein that promotes transcription and MMP7 regulates and supports tumor proliferation and the inhibition of apoptosis." (PMID 36769287, 2023). "According to some studies, suppressing YAP1 and TAZ can inhibit in vitro tumor sphere formation, 3D-matrigel growth, and migration of special cancer cells." (PMID 37444578, 2023). "This hinted that the knockdown of the major NANOG target gene YAP1 had the most potent effect on HBX and NANOG-mediated anti-tumor effect." (PMID 37744383, 2023). "In a small cohort of human CRC patient tissues, YAP1 and MUC13 showed increased expression in tumor samples (stages I, II, III, and IV)." (PMID 37793774, 2023). "YAP1 and TAZ are critical members of the Hippo signalling pathway and reportedly serve as a key point in carcinogenesis and the tumour microenvironment." (PMID 37665055, 2023). "On the other hand, USP10 overexpression promoted YAP1 expression, improved EMT, and simultaneously increased distant tumor metastasis." (PMID 37184153, 2023). "Moreover, researchers speculated that since both genes, namely YAP1 and MAML2 are located in chromosome 11p and both YAP1-MAML2 and MAML2-YAP1 fusions often occur simultaneously in the same tumor, fusions related to YAP1 and MAML2 reflect an intrachromosomal inversion." (PMID 37627947, 2023). "By subcutaneous tumor analysis, we found that overexpression of TPM2 suppressed the expression level of YAP1, especially the staining abundance in the nucleus." (PMID 36823643, 2023). "Impaired degradation of YAP1 and IL6ST by either the ubiquitin-proteasome system or autophagy was shown to favor the growth of different tumor types." (PMID 35435804, 2023). "The patient’s tumor contained both an invasive and a preinvasive OSSN component, and both had YAP-1 overexpression." (PMID 37476371, 2023). "YAP1 protein expression seems also to correlate with the stage of disease, with highest expression in limited stage SCLC, an inflamed tumour microenvironment, and a better prognosis 23•]." (PMID 37870696, 2023). "In the Hippo signaling pathway, YAP1, along with TAZ, activates TEADs, thus affecting cell proliferation, organ size, drug sensitivity, and the tumor microenvironment (TME)." (PMID 37752152, 2023). "YAP1 activity, particularly its phosphorylation level, is commonly regulated by the LATS1/2 kinase of the Hippo pathway and is critical for tumor initiation, progression, and metastasis." (PMID 36735162, 2023). "Previous studies revealed the significance of YAP1 and TFE3 for carcinogenesis in several tumor entities, such as liver cancer, breast cancer, prostate cancer or renal cancer." (PMID 36749424, 2023).
tumor (continued). "We observed strong focal staining of YAP1 and WWTR1 in a subpopulation of cells within a tumor section that was otherwise positive for H&E and ATOH1 (red arrows)." (PMID 36719743, 2023). "The results revealed that the expression of YAP1 and its downstream target genes was markedly decreased in RNF146‐knockdown HGC‐27 cells and xenograft tumours." (PMID 37555915, 2023). "In detail, we observed the presence of YAP1+ (Fig EV3E′ and F′) and p75 NGFR+ (Fig EV3E′′ and F′′) cells in SHH MB‐derived PDOs (tumor #9 and #10)." (PMID 38037472, 2023). "This dynamic interplay between YAP1 and the ECM composition not only perpetuates tumour growth and metastasis but also poses resistance to chemotherapy." (PMID 37983931, 2023). "The YAP1::TFE3 fusion was identified in one case (#130), and this tumour demonstrated unique morphology compared to tumours harbouring the more common WWTR1::CAMTA1 fusion." (PMID 37686662, 2023). "Histological analysis indicated that the expression of YAP1, TAZ, p62/SQSTM1 and vimentin was also elevated in the tumour tissues of hyperglycemic mice." (PMID 37665055, 2023). "This study also proposed YAP1 upregulation as a biomarker of poor initial response to BRAF and MEK inhibition in BRAFV600E tumor patients." (PMID 37834284, 2023). "Staining for YAP1 and WWTR1 revealed a few rare cells that were positive within the tumor sections assessed." (PMID 36719743, 2023). "BAP1 is identified to inhibit tumor proliferation by stabilizing LATS, while tripartite motif-containing 29 (TRIM29) directly binds to YAP1 and avoids YAP1 from ubiquitinated degradation." (PMID 38174069, 2023). "The increase of CENPK expression further activates the expression of YAP1, which leads to the activation of CRC tumor signal pathway." (PMID 37370088, 2023). "Pharmacologic inhibition of YAP1 specifically reduced CSC-like properties and suppressed tumor growth in YAP1high PC cells, especially in combination with cytotoxic agents in an in vivo patient-derived xenograft (PDX) model." (PMID 37612741, 2023). "Recent studies indicate the tumor-suppressive role of VGL, and this role relies on its competition with YAP1 for binding to TEAD." (PMID 37444578, 2023). "Incorporating these EVs by bystander tumor cells resulted in decreased proliferation and viability, accompanied by a reduction in CCND1 and YAP1 mRNA levels." (PMID 37174717, 2023). "Pharmacological inhibitor of YAP1 suppresses EMT and tumor metastasis upon CXCR7 activation in vivo in tumor xenografts of nude mice and inflammatory colonic adenocarcinoma models." (PMID 36210463, 2022). "Although YAP1 and TAZ are paralogs, we found that YAP1 exhibited a tumor suppressive role, whereas TAZ exhibited a tumor promoting role using both in vitro and in vivo tumorigenesis assays." (PMID 35930163, 2022). "In the subcutaneous tumor samples, IHC staining showed that overexpression of MT2A promoted the expression of phosphorylated MST1 and YAP1 compared to the control." (PMID 35642057, 2022). "KRAS signaling can affect tumor proliferation by two independent pathways: one is the MAPK/ERK and PI3K/AKT signaling pathway and the other is YAP1 and c-myc, both of which were involved in cell cycle actions." (PMID 36144542, 2022). "Correspondingly, the number of the tumor sphere and percentage of CD44+/CD24−/low population were significantly increased in LIN28A knockdown CAL51 cells followed by YAP1 overexpression." (PMID 35102250, 2022). "Conversely, Sox9 (a Wnt and Yap1-target gene) and some canonical targets of Yap/Tead such as Cyr61 and IL33 which have known roles in stem cell maintenance, cell migration and tumor invasiveness - were repressed by AHR." (PMID 35383166, 2022).